CHI3L1 (chitinase 3 like 1)
Diseases named in the same sentence as CHI3L1 in open-access papers (continued):
Sharing a sentence is not in itself a finding about the gene and the disease.
asthma (continued). "We demonstrate that genetic variation of CHI3L1 is associated with asthma in early childhood." (PMID 27193312, 2016). "We assessed in an unselected population whether SNPs in CHI3L1 and cord blood YKL-40 levels at birth are associated with respiratory symptoms, lung function changes, asthma, and atopy." (PMID 27193312, 2016). "Another study found a different YKL-40/CHI3L1 variant associated with asthma." (PMID 26542293, 2015). "Interestingly, top-listed differentially expressed Th17-associated genes S100B, MILR1 and CHI3L1 have been reported to play roles in allergy and asthma." (PMID 24991220, 2014). "In fact, we are the first to demonstrate that the CHI3L1 polymorphisms rs1538372 and rs10399931 in the Taiwanese population were not only significantly associated with asthma risk, but also related to serum YKL-40 concentrations with a gene-dose dependent relationship." (PMID 25056157, 2014). "We found that the CHI3L1 polymorphisms rs1538372 and rs10399931 had an r2 of 0.84 in a linkage disequilibrium plot and a nominally significant association with asthma (P < 0.05)." (PMID 25056157, 2014). "Adjusted odds ratios of the CHI3L1 rs1538372 CC genotype (aOR = 1.97, 95% CI: 1.23–3.14) and the rs10399931 GG genotype (aOR = 1.77, 95% CI: 1.13–2.77) were significantly associated with asthma in the Taiwanese populations." (PMID 25056157, 2014). "We included CCL26 (eotaxin-3) and CHI3L1 (chitinase-3-like-1) expression in this panel, as in addition to their involvement in asthma pathogenesis, their expression is also linked to epithelial differentiation, with both being members of gene families identified as potential asthma biomarkers." (PMID 23402658, 2013). "Thus, the inhibition of CHI3L1 DNA variants could contribute to the lower production of circulating CHI3L1 and decrease the risk of asthma and airway remodeling." (PMID 38667293, 2024). "In addition, specific subgroups of Chi3l1 are associated with the severity of asthma." (PMID 39769202, 2024). "Additionally, elevated levels of CHI3L1(YKL40) have also been associated with an increased risk of frequent acute exacerbations, the poor control of airway symptoms, and the clinical prognosis of asthma." (PMID 38543093, 2024). "However, Chi3L1 is associated with inflammation, fibrosis, solid tumors, and asthma." (PMID 34861103, 2022). "In the current study, stronger association was found in adult asthma patients who developed the disease at 41 years of age or older, which may indicate that some CHI3L1 SNPs have an opposite or independent effect on the risk of asthma later in life as compared with early-onset asthma." (PMID 30940096, 2019). "The G allele of CHI3L1 rs4950928 might be a protective factor against the development of asthma." (PMID 29233108, 2017). "Interestingly, the C-allele of the -131 C→G (rs4950928) polymorphism of CHI3L1 has been shown to associate with bronchial hyperresponsiveness and reduced lung function suggesting that variations in CHI3L1 may influence risk of asthma." (PMID 19568425, 2009). "Particularly in cases of asthma and COPD, CHI3L1 is associated with the resolution of inflammation, tissue remodeling, and immune response control." (PMID 39806495, 2025). "In our cohort, comprising healthy controls and patients with AA and NA, we confirmed a significant decrease in CHI3L1 gene expression in PBMCs from asthma patients compared to controls, consistent with prior findings." (PMID 41154593, 2025). "In summary, despite sample size limitations, our data indicate a potential involvement of DNA methylation in regulating CHI3L1 expression in asthma, though other regulatory mechanisms likely contribute." (PMID 41154593, 2025). "In conclusion, our bioinformatics analysis identified NOS2, TCN1, CHI3L1 and TIMP1 as potential diagnostic biomarkers for asthma and UC." (PMID 40443529, 2025).
asthma (continued). "When gene and protein expression were analyzed by asthma severity (patients with severe asthma vs. moderate or mild asthma), we observed that CHI3L1 gene expression was lower in severe patients compared to moderate–mild patients in both NA and AA groups." (PMID 41154593, 2025). "CHI3L1, a 40-kDa proinflammatory glycoprotein, plays a role in the pathophysiology of various conditions including asthma, inflammatory diseases, cancers, and cardiovascular diseases." (PMID 40044787, 2025). "Studies have shown that the expression of CHI3L1 is significantly upregulated in various inflammatory diseases, including chronic enteritis, pneumonia, asthma, and arthritis." (PMID 41008172, 2025). "Asthma results showed that the expression of CHI3L1 was positively correlated with Monocytes, Macrophages M0 and Neutrophils, while on the contrary, CHI3L1 was negatively correlated with Plasma cells and Mast cells resting." (PMID 40443529, 2025). "For instance, periostin and chitinase-like protein YLK-40, the latter also known as chitinase 3 like 1 (CHI3L1), are recognised as asthma biomarkers in developed regions, but few studies have evaluated their levels in populations exposed to tropical parasites." (PMID 40943268, 2025). "Elevated CHI3L1 levels are found in eosinophilic respiratory diseases like asthma, serving as a biomarker for disease severity." (PMID 38975344, 2024). "A significant amount of evidence has revealed a close correlation between serum Chi3l1 levels and the diagnosis and severity of asthma." (PMID 39769202, 2024). "A wide range of studies have elucidated a robust correlation between CHI3L1 expression levels and the severity as well as prognostic outcomes of diseases, including asthma, atopic dermatitis, and interstitial lung disease." (PMID 38667293, 2024). "Murine studies have found that CHI3L1 was induced by a high-fat diet and Th2 inflammation (such as asthma) and contributes to the genesis of obesity." (PMID 38667293, 2024). "A positive correlation between CHI3L1(YKL40) expression levels, the degree of airflow limitation, and the severity of symptoms has been noted in asthma patients." (PMID 38543093, 2024). "Elevated levels of CHI3L1 have been observed in several chronic inflammatory diseases, including asthma, where it is thought to contribute to disease pathogenesis through its effects on immune cell recruitment, tissue remodeling, and fibrosis." (PMID 38975344, 2024). "A novel intronic SNP, rs12141494, alters airway CHI3L1 expression to contribute to the severity of asthma and airway remodeling." (PMID 38667293, 2024). "A prospective cohort design found that serum CHI3L1 level relates to the increase of the risks from moderate to severe asthma exacerbations and can be a predictor of moderate to severe asthma exacerbation." (PMID 38667293, 2024). "Another study reported that treatment with a humanized anti-IL-5 monoclonal antibody called mepolizumab (MEP) can attenuate allergen-induced Th2 inflammation and tissue remodeling by downregulating Chi3l1 levels in asthma patients." (PMID 39769202, 2024). "Various studies have explored the potential of blocking CHI3L1(YKL40) activity or neutralizing its effects to reduce airway inflammation and improve asthma symptoms." (PMID 38543093, 2024). "CHI3L1/YKL40 genetic variants were demonstrated to impact its messenger (m)RNA expression and exhibit strong associations with various diseases, including asthma, Alzheimer's disease (AD), atopy and hypertension." (PMID 37902124, 2023). "Data from patient cohorts and mouse models of atopic dermatitis, food allergy and asthma strongly support a role for chitinase-3-like-1 protein (CHI3L1) in allergic disease." (PMID 37575256, 2023). "Levels of YKL-40 (the protein product of the human CHI3L1 gene) and expression of CHI3L1 are increased in the lungs and serum of some asthma patient cohorts." (PMID 37575256, 2023).
asthma (continued). "As a member of the chitinase protein family, CHI3L1 (YKL-40) has been found to be significantly elevated in various diseases, such as liver fibrosis, endometrial cancer, and asthma." (PMID 38003338, 2023). "In agreement with human patient studies, experiments using Chi3l1-/- mice reveal that Chi3l1 regulates type 2 cytokines and IgE levels in mouse models of asthma, atopic dermatitis and food allergy." (PMID 37575256, 2023). "A study on mice and human subjects found that CHI3L1 gene expression and the protein generated by its activation (chitinase 3-like 1) can be induced by a high-fat diet and thereby contribute both to obesity and to asthma development." (PMID 33418879, 2021). "CHI3L1 gene was reported to play an important role in asthma, bronchial hyper‐responsiveness, abnormal lung function and hepatitis C virus–induced liver fibrosis." (PMID 33280245, 2021). "CHI3L1 is specifically expressed in diseases involving inflammation, such as inflammatory bowel disease, hepatitis, and asthma." (PMID 33222690, 2020). "A subgroup of adults with asthma with high chitinase 3-like 1 (CH3L1, also called YKL-40) was prone to have adult-onset and frequent asthma exacerbations, suggesting an association between OPN and CH3L124." (PMID 32009132, 2020). "An interesting observation is the correlation between IL-33 and CHI3L1 (YKL-40) mRNA expression in asthma and COPD suggesting possible common pathways of these two mediators." (PMID 32842623, 2020). "In any case, our finding cannot stand alone but should be seen as a contribution to the discussion about the genetic role of CHI3L1 in asthma." (PMID 30940096, 2019). "Association was also found between variants in chitinase 3-like 1 (CHI3L1; YKL-40) and asthma exacerbations and hospitalizations." (PMID 31443563, 2019). "Studies of this have added to our understanding of the importance of genetic variations by demonstrating that CHI3L1 rs4950928 and rs1214194 genotypes play a critical role in early-onset adult asthma." (PMID 29618952, 2018). "Previous studies have indicated that chitinase 3-like 1 (CHI3L1) gene rs4950928 polymorphism and acidic mammalian chitinase (AMCase or CHIA) gene rs10494132 polymorphism are associated with the risk of asthma." (PMID 29233108, 2017). "Using animal models of asthma and obesity, Ahangari and collaborators demonstrated that a high fat diet and Th2 inflammation induce Chi3l1 in visceral adipose tissue and pulmonary tissues, respectively." (PMID 28696379, 2017). "From cross-sectional studies it is well known that both, genetic variation in CHI3L1 and YKL-40 levels are associated with asthma, atopy, and lung function measures." (PMID 27193312, 2016). "The protective effect of rs10399931[A] for asthma at 6 years, although non-significant after adjusting for multiple testing, provided further evidence for the relevance of genetic variation in CHI3L1 for asthma development." (PMID 27193312, 2016). "Single nucleotide polymorphisms (SNPs) in chitinase 3-like 1 (CHI3L1), the gene encoding YKL-40, and increased serum YKL-40 levels are associated with severe forms of asthma." (PMID 27193312, 2016). "Increased levels of CHI3L1 protein and/or mRNA have been shown in patients with a broad spectrum of diseases including asthma, inflammatory bowel disease (IBD) and arthritis where they reflect the activity and natural history of the disease." (PMID 27826220, 2016). "Genetic studies revealed that variation in the gene encoding YKL-40, chitinase 3-like 1 (CHI3L1), contributes to the pathogenesis of asthma." (PMID 27193312, 2016). "Studies have shown a relationship between asthma, serum YKL-40, and the single nucleotide polymorphism (SNP) (−131 C/G, rs4950928) in the CHI3L1 gene that codes for YKL-40." (PMID 26672955, 2015). "Single nucleotide polymorphisms in CHI3L1 promoter were found to be associated with elevated YKL-40 levels as well as atopy, asthma, and bronchial hyperresponsiveness." (PMID 25663327, 2015).
asthma (continued). "More research is needed to clarify the relationship between different asthma phenotypes, YKL-40, and CHI3L1." (PMID 26672955, 2015). "CHI3L1, which encodes the YKL-40 protein, is associated with asthma in Western European and American populations and with atopy in a Korean population." (PMID 25056157, 2014). "A single nucleotide polymorphism in the promoter of the CHI3L1 gene (-131 C → G) of patients with asthma was correlated with elevated serum YKL-40, bronchial hyper reactivity, and pulmonary function." (PMID 24373580, 2013). "Several studies on SNPs of the YKL-40 encoding gene, CHI3L1, have documented that genetic variations of CHI3L1 have an impact on circulating YKL-40-levels, both in healthy adults as well as in individuals with asthma, sarcoidosis, rheumatoid arthritis and CAD." (PMID 23071724, 2012). "The relationships between CHI3L1 polymorphisms and YKL-40 production have been studied in a small number of patients with various inflammatory disorders, such as sarcoidosis, asthma, hepatitis, schizophrenia and diabetes." (PMID 21714862, 2011). "Investigation by a group at Yale, showed that asthma severity can be correlated with YKL-40 (chitinase 3-like-1) levels." (PMID 23283176, 2011). "The promoter SNP g.-131(C > G) in the CHI3L1 gene was associated with elevated serum YKL-40, asthma, bronchial hyper responsiveness and pulmonary function, and with elevated serum YKL-40 and the severity of hepatitis C virus-induced liver fibrosis." (PMID 21714862, 2011). "YKL-40 (alternatively called HCgp39 or CHI3L1) is observed in elevated levels for patients with severe asthma, cardiovascular disease and diabetes, cancer, peritoneal endometriosis, morbid obesity, osteoarthritis, and liver fibrosis." (PMID 20559485, 2010). "It has been shown by others that differentiated macrophages do express CHI3L1 in vitro and in vivo in peritumoral macrophages in small cell lung cancer, in atherosclerotic plaques or in an asthma model in mice." (PMID 20540736, 2010). "Pairwise these SNPs could account for a part of the role of CHI3L1 in asthma; however the nominally associations of the individual SNPs does not add up to genotypes that are associated with both clinical informations and symptoms of asthma and/or atopy as well as measures of lung function." (PMID 19568425, 2009). "This is the first large-scale study of variation in CHI3L1 in relation to asthma and atopy in a population-based sample of adults." (PMID 19568425, 2009). "Similarly, associations between CHI3L1 polymorphisms, circulating YKL-40 levels, and asthma features vary across studies, possibly due to population genetic differences." (PMID 41154593, 2025). "Elevated CHI3L1 levels have been detected in the serum and lungs of asthma patients." (PMID 40443529, 2025). "In addition, we identified NOS2, TCN1, CHI3L1, and TIMP1 as possible diagnostic markers for UC and asthma." (PMID 40443529, 2025). "Regarding asthma, CHI3L1 plays a key role in CD4+ T cell polarization and Th2 inflammation." (PMID 41154593, 2025). "The level of CHI3L1(YKL40) is correlated with disease severity in asthma patients." (PMID 38543093, 2024). "Chi3l1 siRNA also decreases the expression of eosinophilic airway inflammation-related factors, including IL-5, eotaxin, and GM-CSF, at the mRNA and protein levels in an epithelial cell model of asthma, thus reducing airway inflammation." (PMID 39769202, 2024). "The respiratory tract functions as a passage for gas, and its associated inflammatory diseases (e.g., chronic obstructive pulmonary disease, asthma, bronchiolitis, obstructive sleep apnea syndrome, and rhinitis) are also related to increased serum levels of Chi3l1." (PMID 39769202, 2024). "Previous studies have found that CHI3L1(YKL40) expression levels are significantly elevated in asthma patients, and it may play an important role in the pathogenesis of asthma." (PMID 38543093, 2024).
asthma (continued). "However, the underlying mechanism of CHI3L1(YKL40) in asthma is not fully understood; thus, it is necessary to understand the complex roles of CHI3L1(YKL40) in asthma pathogenesis and its potential as a target for treatment." (PMID 38543093, 2024). "Similarly, circulating CHI3L1 levels were also elevated in asthma patients compared with healthy controls and positively correlated with the severity of asthma." (PMID 38667293, 2024). "Similarly, experiments using Chi3l1-/- mice show that Chi3l1 regulates type 2 cytokines and IgE in models of asthma, atopic dermatitis and food allergy." (PMID 37575256, 2023). "In addition, a previous study using a mouse model of ovalbumin-induced asthma revealed that exposure to graphene oxide increased macrophage production of chitinases, CHI3L1, and AMCase39." (PMID 35778420, 2022). "Nevertheless, CHI3L1 SNPs were not significantly related to asthma and association with exacerbation was not investigated in children." (PMID 33925009, 2021). "They specifically identified a single nucleotide polymorphism in the CHI3L1 promoter region that could be used to predict asthma and serum YKL-40 levels." (PMID 33324573, 2020). "We determined whether cis-expression quantitative trait loci (eQTLs) of the gene that encodes YKL-40, chitinase 3-like 1 (CHI3L1), are involved in the onset of asthma or in specific asthma phenotypes." (PMID 30940096, 2019). "This inflammaging may partly explain why the genetic effect of CHI3L1 was especially evident in asthma patients with disease onset at an older age." (PMID 30940096, 2019). "CHI3L1 has been positively correlated with NO levels in tissue culture supernatant from herniated lumbar discs, and exhaled NO in children with severe therapy-resistant asthma." (PMID 29448936, 2018). "AMCase and the chitinase-like protein YKL-40/chitinase 3-like 1 (CHI3L1), which lacks chitinase activity, were shown to play a critical role in inflammation driven by Th2-type cells and were expressed at high levels in tissues from patients with asthma." (PMID 29618952, 2018). "However, more recently it has been described in a large group of patients with asthma, that serum concentrations of CHI3L1 were only slightly increased in those with the most severe asthma." (PMID 29977241, 2018). "Therefore, it is important to perform a meta-analysis of all eligible studies to clarify the effects of CHI3L1 rs4950928 polymorphism and CHIA rs10494132 variant on risk of asthma." (PMID 29233108, 2017). "Firstly, sample size in this meta-analysis was small, which might result in bias of the results when evaluating the association of CHI3L1 and CHIA gene polymorphisms with susceptibility to asthma." (PMID 29233108, 2017). "After a systematical literature search based on the inclusion criteria, 10 case-control studies from 8 published articles containing 1858 cases and 1778 controls were identified for this meta-analysis to investigate the relations of CHI3L1 and CHIA variants with asthma risk." (PMID 29233108, 2017). "Therefore, a systematic meta-analysis was important to clarify the effect of CHI3L1 rs4950928 polymorphism and CHIA rs10494132 variant on asthma risk." (PMID 29233108, 2017). "Given its route of transmission and tropism for alveolar macrophages, factors that have not been previously reported appear to be relevant to OPPV disease, such as lung cancer biomarker (SAA1), asthma biomarker (CHI3L1), and neuro-inflammation complement factor (CFB)." (PMID 26950733, 2016). "The role of YKL-40/CHI3L1 SNPs for asthma was further confirmed in a Taiwanese population." (PMID 26542293, 2015). "There was no increased risk of asthma associated with different genotypes on the SNP (−131 C/G, rs4950928) in the CHI3L1 gene in our study." (PMID 26672955, 2015). "None of the remaining investigated variations of CHI3L1 were significantly associated with asthma, atopy or asthma-related traits or with measures of lung function." (PMID 19568425, 2009).